PLCL1 (phospholipase C like 1 (inactive))
Description:
Involved in an inositol phospholipid-based intracellular signaling cascade. Shows no PLC activity to phosphatidylinositol 4,5-bisphosphate and phosphatidylinositol. Component in the phospho-dependent endocytosis process of GABA A receptor (By similarity). Regulates the turnover of receptors and thus contributes to the maintenance of GABA-mediated synaptic inhibition. Its aberrant expression could contribute to the genesis and progression of lung carcinoma. Acts as an inhibitor of PPP1C.
Synonyms: PRIP; PLC-L; PLCL; PPP1R127; PLCE; PLDL1
Tractability: PROTAC: its protein half-life has been measured.
Gene: Protein-coding gene on chromosome 2 (197,804,593 to 198,572,581, forward strand). Ensembl gene ENSG00000115896.
Subcellular location: Cytoplasm
Gene Ontology:
Molecular function: phospholipase C activity; phosphatidylinositol-4,5-bisphosphate phospholipase C activity; phosphoric diester hydrolase activity
Biological process: gamma-aminobutyric acid signaling pathway; intracellular signal transduction; negative regulation of cold-induced thermogenesis; phosphatidylinositol metabolic process; phosphatidylinositol-mediated signaling; regulation of synaptic transmission, GABAergic; release of sequestered calcium ion into cytosol; lipid metabolic process; signal transduction
Cellular component: cytoplasm
Genetic constraint (gnomAD): Loss-of-function variants: 37 observed, 73.46 expected, observed/expected ratio (o/e) 0.5, 90% interval 0.39 to 0.66. The upper end of that interval is the gene's LOEUF score, 0.66, which puts it in group 2 of 6, group 1 being the genes least tolerant of losing a copy. Missense variants: 1,128 observed, 1,294.6 expected, observed/expected ratio (o/e) 0.87, 90% interval 0.83 to 0.92. Synonymous variants: 465 observed, 465.4 expected, observed/expected ratio (o/e) 1, 90% interval 0.93 to 1.08.
Homologues: Orthologues: chimpanzee PLCL1 (99% identical), macaque PLCL1 (99% identical), dog PLCL1 (97% identical), rabbit PLCL1 (95% identical), mouse Plcl1 (95% identical), rat Plcl1 (94% identical), pig PLCL1 (91% identical), guinea pig PLCL1 (84% identical), tropical clawed frog PLCL1 (77% identical), zebrafish plcl1 (55% identical), Caenorhabditis elegans pll-1 (39% identical), Caenorhabditis elegans plc-3 (24% identical), and 3 more. Paralogues in human: PLCL2 (64% identical), PLCH2 (33% identical), PLCH1 (32% identical), PLCD4 (26% identical), PLCD1 (26% identical), PLCE1 (26% identical), PLCB1 (24% identical), PLCB4 (24% identical), PLCD3 (23% identical), PLCB3 (23% identical), PLCB2 (23% identical), PLCG2 (22% identical), and 2 more.
Diseases named in the same sentence as PLCL1 in open-access papers:
PLCL1 is named in the same sentence as 58 diseases in open-access papers, as found by Europe PMC text mining. Sharing a sentence is not in itself a finding about the gene and the disease. The quoted sentences say what the papers report.
clear cell renal cell carcinoma (5 papers, 2019 to 2025). "The downregulation of PLCL1 expression in clear cell renal carcinoma and neuroblastoma was found to be predictive of poor prognosis." (PMID 36276067, 2022). "By screening three independent lipid metabolism‐related gene sets in clear cell renal cell carcinoma (ccRCC) and analyzing the TCGA database, it is found that PLCL1 predicted a poor prognosis and was downregulated in ccRCC." (PMID 31131187, 2019). "PLCL1 is downregulated in clear cell renal carcinoma (ccRCC) and predicted a poor prognosis." (PMID 32762776, 2020). "PLCL1 was demonstrated to induce abnormal lipid metabolism in tumor cells by interacting with metabolism-related gene uncoupling protein 1 (UCP1), thereby repressing progression of clear cell renal cell carcinoma (ccRCC)." (PMID 36389725, 2022).
autoimmune disease (3 papers, 2017 to 2025). A disorder resulting from loss of function or tissue destruction of an organ or multiple organs, arising from humoral or cellular immune responses of the individual to their own tissue constituents. "However, variants of the PLCL1 gene had been proven to be associated with other autoimmune diseases, such as Crohn’s disease (CD), systemic lupus erythematosus (SLE)." (PMID 28854271, 2017). "We identified 12 pleiotropic genes, including PLCL1, SPRED1, and CNNM2, associated with the comorbidity of DeP and autoimmune diseases." (PMID 41212883, 2025). "PLCL1 not only directly regulates immune cells and inflammatory factors but also impacts the development and progression of autoimmune diseases by interacting with other immune-related pathways." (PMID 41212883, 2025).
asthma (2 papers, 2020 to 2025). "We further evaluated the expression of PLCL1 in asthma, RA, or DeP patients and controls." (PMID 41212883, 2025). "In addition, we found that PoPS of PLCL1 was greater than 1 in the DeP-asthma (Score = 2.62) and DeP-RA (Score = 2.16) trait pairs." (PMID 41212883, 2025). "Notably, in thyroid tissues, we identified a significant regulatory role for the gene PLCL1 in the comorbidities of both DeP (P = 4.29 × 10−6) and asthma/RA (Pasthma = 1.07 × 10−4 and PRA = 3.90 × 10−3)." (PMID 41212883, 2025). "Notably, PLCL1 plays a significant regulatory role in DeP, asthma, and RA." (PMID 41212883, 2025). "The Kolmogorov-Smirnov test indicated that PLCL1 expression was higher in the individuals of asthma with DeP, asthma without DeP, and only DeP than that in the control (P = 5.0 × 10−3)." (PMID 41212883, 2025).
eosinophilic esophagitis (2 papers, 2014 to 2015). Eosinophilic esophagitis (EoE) is a chronic, allergic disease of the esophagus characterized clinically by symptoms of esophageal dysfunction (including vomiting, dysphagia, feeding disorders, food impaction and abdominal pain) which persist after treatment with proton pump inhibitors (PPIs). "Namjou and colleagues applied the same approach to European-origin pediatric cohorts and discovered genetic links between the phospholipase C-like 1 gene PLCL1 and speech language development, and between the interleukin gene cluster IL5-IL13 and eosinophilic esophagitis." (PMID 25937834, 2015).
gastric cancer (2 papers, 2019 to 2022). A primary or metastatic malignant neoplasm involving the stomach. "These molecular characteristics were mainly driven by the eight NRGPI oncogenes (CYTL1, PLCL1, CNTN1, GRP, APOD, GPX3, FCN1, SERPINE1) as validated in the gastric cancer cell lines and clinical samples." (PMID 36389725, 2022).
idiopathic pulmonary fibrosis (2 papers, 2025). Idiopathic pulmonary fibrosis (IPF) is a nonneoplastic pulmonary disease that is characterized by the formation of scar tissue within the lungs in the absence of any known cause. "‘COL23A1+ adventitial fibroblasts’ shared key markers (COL15A1, ENTPD1, PLCL1) with peribronchial fibroblasts, a subpopulation specifically localized around the airway epithelium, which is enriched in idiopathic pulmonary fibrosis and may be implicated as a key cell type in lung disease." (PMID 40114924, 2025). "We defined significant genetic overlap between DeP and ADs, particularly idiopathic pulmonary fibrosis (IPF), rheumatoid arthritis (RA), and ulcerative colitis (UC), with shared loci and genes, such as rs7171171 and PLCL1." (PMID 41212883, 2025).
kidney cancer (2 papers, 2019 to 2022). Primary or metastatic malignant neoplasm involving the kidney. "PLCL1 was downregulated in kidney cancer tissues and correlated with a poor prognosis." (PMID 36189312, 2022). "In addition, PLCL1 could repress the progression of kidney cancer through UCP1-mediated lipid browning." (PMID 36189312, 2022).
myositis (2 papers, 2018 to 2024). "In large scale case-control studies in a Chinese Han population using candidate gene approach, CCL21, a myositis susceptibility gene in Caucasians, was found to associate with PM or PM-associated ILD, TNFAIP3 and IRF5 with myositis or myositis-associated ILD, and PLCL1 with DM and DM-associated ILD." (PMID 29854780, 2018).
neuroblastoma (2 papers, 2022 to 2024). Neuroblastoma (NB) is the most common solid, extracranial childhood tumor. "A previous study showed that the upregulation of PLCL1, mediated by the overexpression of CHD5, could suppress the invasion and migration of neuroblastoma cells." (PMID 38561388, 2024).
osteoporosis (2 papers, 2008 to 2011). A condition of reduced bone mass, with decreased cortical thickness and a decrease in the number and size of the trabeculae of cancellous bone (but normal chemical composition), resulting in increased fracture incidence. "In our GWAS sample, the PLCL1 gene's association with hip BS was limited only to women, suggesting female-specificity of this gene's importance to osteoporosis." (PMID 18776929, 2008). "Since osteoporosis incidence was found to be inversely associated with BMI, we also examined the influence of BMI on the PLCL1 gene's association with hip BS." (PMID 18776929, 2008). "Comparison of our GWAS data with SNPs identified in previous GWASs on osteoporosis showed five SNPs in three genes (PLCL1, DOK6, and MEF2C) with P values below 0.05." (PMID 21573128, 2011). "In the female subjects of our GWAS cohort, we also analyzed the PLCL1 gene's importance to other phenotypes relevant to osteoporosis, including hip and spine BMD, spine BS and height." (PMID 18776929, 2008).
prostate carcinoma (2 papers, 2020 to 2023). A carcinoma that arises from epithelial cells of the prostate gland. "PLCL1 has been nominally associated with prostate cancer through a SNP x SNP interaction study." (PMID 32986714, 2020).
autism (1 paper, 2023). Persistent deficits in social interaction and communication and interaction as well as a markedly restricted repertoire of activity and interest as well as repetitive patterns of behavior. "As another example, rs7580864 on 2q33.1 is an eQTL of PLCL1 that is implicated in autism, a neurodevelopmental disorder that often affects language and social skills." (PMID 36800424, 2023).
bipolar disorder (1 paper, 2024). A disorder of the brain that causes unusual shifts in mood, energy, activity levels and the ability to carry out day-to-day tasks. "Genes that were associated with brain volumes, depression, and schizophrenia or bipolar disorder includedAC011997.1,AKT3,BANK1,BOLL,DCC,HSPD1,HSPE1,HSPE1-MOB4,MOB4,PLCL1,RFTN2,SF3B1, andTRPS1." (PMID 40800518, 2024).
coronary artery aneurysm (1 paper, 2020). "In addition to these studies, PLCL1 has been implicated in coronary artery aneurysm in Kawasaki disease and PLCL1 might play a role in the regulation of vascular endothelial cell inflammation via interference with proinflammatory cytokine expression." (PMID 33186364, 2020).
Developmental Delays (1 paper, 2014). "Another neurodevelopmental association effect was observed in the vicinity of the Phospholipase C-Like 1 (PLCL1, PRIP-1) gene for overall Developmental Delays-Speech and Language Disorder." (PMID 25477900, 2014).
fracture (1 paper, 2009). "In postmenopausal women, our results suggest that the PLCL1 rs7595412 polymorphism has no obvious effect on hip BS and BMD but may be associated with increased proportion of vertebral fracture and increased levels of osteocalcin." (PMID 20030815, 2009).
idiopathic inflammatory myopathies (1 paper, 2023). "Previous findings have primarily focused on the structure of PLCL1, indicating that genetic single nucleotide polymorphisms of PLCL1 are correlated with hip bone size in females and idiopathic inflammatory myopathies." (PMID 37801481, 2023).
Immunodeficiency (1 paper, 2022). Failure of the immune system to protect the body adequately from infection, due to the absence or insufficiency of some component process or substance. "Therefore, it is reasonable to postulate that the dysregulation of PAK2, TAP2, and PLCL1 genes is likely to elicit autoimmune reactions by altering antigen processing and presentation, T cell receptor signaling, and immunodeficiency pathways." (PMID 35783297, 2022).
juvenile dermatomyositis (1 paper, 2021). Juvenile dermatomyositis (JDM) is the early-onset form of dermatomyositis (DM), a systemic, autoimmune inflammatory muscle disorder, characterized by proximal muscle weakness, evocative skin lesion, and systemic manifestations. "The genetic variant rs74688411 lies in the intron of the phospholipase C like 1 (PLCL1) gene that has been reported by GWAS of adult and juvenile dermatomyositis, hip bone size variation in women, and total bone mineral density." (PMID 34214102, 2021).
primary immunodeficiency (1 paper, 2022). "TAP2 is associated with Antigen processing and presentation, and primary immunodeficiency, and PLCL1 in GABAergic synapse, and T cell receptor signaling pathway." (PMID 35783297, 2022).
renal cell carcinoma (1 paper, 2023). "A previous study showed that phospholipase C-like protein 1 (PLCL1) is associated with lipid metabolism in renal cell carcinoma (RCC)." (PMID 37801481, 2023).
sarcoidosis (1 paper, 2025). Sarcoidosis is a multisystemic disorder of unknown cause characterized by the formation of immune granulomas in involved organs. "Of great interest, PLCL1, PPARG, CD19 have been involved in sarcoidosis through functional studies." (PMID 41466414, 2025).
tobacco use disorder (1 paper, 2026). "The other five loci contained promising coding and expression variants, including Trak2, a gene previously associated with CUD in human GWAS and Slc10a7, Plcl1, and Satb2 which have been associated with alcohol and tobacco use disorder." (PMID 42277005, 2026).
tumor (17 papers, 2015 to 2025). "Our previous study showed that lipid browning mediated by PLCL1/UCP1 promotes tumor cell “slimming” and causes abnormal lipid accumulation, which represses the progression of ccRCC." (PMID 38263248, 2024). "PLCL1, as a survival-related gene of GC, is also significantly correlated with clinical characteristics, tumor microenvironment immune cells, tumor mutation burden (TMB), and tumor necrosis factor (TNF)." (PMID 35912206, 2022). "Restoration of PLCL1 expression in ccRCC cells repressed tumor progression, reduced abnormal lipid accumulation, and caused tumor cell “slimming” through UCP1-mediated lipid browning, which consumes lipids without producing ATP energy." (PMID 32762776, 2020). "Previously, we have identified a phenomenon termed the “slimming” effect, wherein restoration of PLCL1 hinders tumor progression and reduces lipid accumulation." (PMID 39039052, 2024). "Compared to the vector group, PLCL1 significantly decreased the tumour volume and weight derived from the xenograft tumour model." (PMID 37801481, 2023). "Bioinformatics analysis of five microarray datasets revealed that expression of PLCL1 is decreased in tumours and is positively correlated with prognosis in RCC patients." (PMID 37801481, 2023). "Simultaneously, the results of orthotopic xenograft models also showed that PLCL1 decreased tumour volume and weight compared to those in control mice." (PMID 37801481, 2023). "Compared to the vector group, overexpression of PLCL1 significantly induced apoptosis of tumour cells, especially the early stage of apoptosis, while the ratio of proliferation was dramatically promoted in 769P cells treated with PLCL1 siRNA." (PMID 37801481, 2023). "Compared to the normal group, PLCL1 expression in tumour samples was significantly decreased at the mRNA and protein levels, and similar results were observed between HK2 and RCC cell lines." (PMID 37801481, 2023). "Together, these results suggest that PLCL1 represses tumour proliferation and invasion in RCC cells." (PMID 37801481, 2023). "Recently, it has been demonstrated that PLCL1 induces abnormal lipid metabolism in tumour cells by interacting with metabolism-related gene uncoupling protein 1 (UCP1), repressing RCC progression." (PMID 37801481, 2023). "Phospholipase C‐like 1 (PLCL1), which is homologous to the PLC family, is associated with tumor growth suppression and metastasis." (PMID 36276067, 2022). "We conclude that PLCL1 repressed the progression of ccRCC and promoted tumor cell “slimming” mainly through UCP1‐mediated lipid browning." (PMID 31131187, 2019). "Oil red staining was then used to show the accumulation of lipid droplets in the xenograft tumor; the results showed that the group overexpressing PLCL1 had reduced lipid accumulation." (PMID 31131187, 2019). "Collectively, we suggest a model in which PLCL1 promotes tumor cell “slimming” by increasing the level of UCP1, allowing cells to consume lipids without producing ATP to repress the progression of ccRCC." (PMID 31131187, 2019). "Further studies show that PLCL1 promotes tumor cell “slimming” and represses tumor progression through UCP1‐mediated lipid browning, which consumes lipids without producing ATP energy." (PMID 31131187, 2019). "Mechanistic and functional research showed that PLCL1 promoted this process and repressed tumor progression through lipid browning mediated by UCP1." (PMID 31131187, 2019). "Restoration of PLCL1 expression in ccRCC cells significantly represses tumor progression and reduces abnormal lipid accumulation." (PMID 31131187, 2019). "Collectively, the data indicate that lipid browning mediated by PLCL1/UCP1 promotes tumor cell “slimming” and consumes abnormal lipid accumulation, which represses the progression of ccRCC." (PMID 31131187, 2019). "Moreover, 786-O cells transfected with lentivirus PLCL1 or vector were injected into the left kidney of mice to establish an orthotopic tumour model (red arrow)." (PMID 37801481, 2023).